FGF2 (fibroblast growth factor 2)
Diseases named in the same sentence as FGF2 in open-access papers (continued):
Sharing a sentence is not in itself a finding about the gene and the disease.
melanoma (continued). "Furthermore, FGF-2 and endostatin are potentially useful biomarkers for early detection during melanoma progression, while VEGF-dependent neovascularization in a mouse melanoma model induced by FGF-2 has been shown." (PMID 38791873, 2024). "Targeting FGF2 to limit melanoma angiogenesis results in decisive anti-melanoma effects, which could lead to novel therapeutic approaches for patients with advanced stages of the disease." (PMID 37108717, 2023). "On the other hand, the top downregulated genes formed 4 subgroups and were related to melanogenesis (Wnt5a, Mitf, Pomc, Mc1r, Kit), melanoma (Fgf9, Fgf12, Fgf2), MAPK signaling pathway (Ncam1, Prkcb, Map3k4, Pla2g4a, Mapk14, Mapk11), and aging (Tgfbr1, Il6, Nox4)." (PMID 36555664, 2022). "Some of the genes involved in both ‘Pathways in cancer’ and ‘Melanoma’ are Fgf2, Fgf5, and Pdgfa." (PMID 36009225, 2022). "Exosomal miR-155-5p derived from melanoma could induce fibroblasts to express proangiogenic factors such as VEGFa, FGF2 and others, giving novel strategies to suppress melanoma proliferation through increased cytokine signaling." (PMID 34900338, 2022). "Melanoma cells secrete other growth factors, including bFGF (FGF2) and PGFs." (PMID 34207884, 2021). "The recombinant ds-Diabody against FGF-2 could effectively inhibit proliferation, migration, and invasion of melanoma and glioma tumor cells stimulated by FGF-2." (PMID 33718141, 2021). "FGF-2 was overexpressed in several tumors including melanoma and glioma." (PMID 33718141, 2021). "Additionally, in xenograft models, ds-Diabody against FGF-2 effectively suppressed melanoma and glioma tumo growth and angiogenesis." (PMID 33718141, 2021). "FGF-2 regulates melanoma cell migration in a SDC4-dependent manner." (PMID 34282767, 2021). "The HOXB7/FGF2 interaction has already been described in melanoma and BT474 cells." (PMID 34063128, 2021). "In this study, our data showed that ds-Diabody against FGF-2 could effectively inhibit melanoma and glioma in vivo." (PMID 33718141, 2021). "In addition, Epac mediates endothelial cells angiogenesis and neighboring Epac-poor melanoma cells migration by cell–cell communication via fibroblast growth factor-2 (FGF-2)-HS interaction." (PMID 32899451, 2020). "Analysis of our patients’ tumors suggested that the FGF2 axis may also be a mechanism of resistance in KIT-mutant melanomas." (PMID 32344828, 2020). "Down-regulation of FGF2 in melanoma cells inhibited proliferation and colony formation." (PMID 31167513, 2019). "FGFR1 was detected in 86%, whereas FGF2 in 45% of primary melanomas." (PMID 31167513, 2019). "It has been shown that the FGF2/FGFR1 signaling is also crucial for melanoma angiogenesis as FGF2 secretion by melanoma cells could induce the mitogenic effects on endothelial cells and fibroblasts." (PMID 31167513, 2019). "In addition to being produced by neighboring fibroblasts and keratinocytes, FGF2 can be synthesized by cells in nevi and melanoma cells." (PMID 31167513, 2019). "Melanoma progression was shown to be accompanied by increased FGF2 expression." (PMID 31167513, 2019). "Fibroblast growth factor 2 (FGF2) is one of the critical regulators of melanoma angiogenesis and metastasis; thus, it might be an effective anti-cancer strategy to explore FGF2-targeting drug candidates from existing drugs." (PMID 31035725, 2019). "FGF-2 produced by melanoma cells has a key role in the conversion of normal B to TAB cells." (PMID 28928360, 2017). "FGF-2 produced by melanoma cells is a natural ligand for FGFR-3." (PMID 28928360, 2017). "In the past, most studies on FGFs in melanoma have concentrated on FGF2 and while - in addition to FGF2 - overexpression of FGF5 mRNA was noted in some melanoma cell lines more than two decades ago, FGF5 protein expression in melanoma tissue and its impact on melanoma growth were never investigated." (PMID 29152117, 2017). "Fgf2 is a critical regulator of melanoma progression and it is expressed by melanoma cells." (PMID 28107390, 2017).
melanoma (continued). "Moreover, levels of circulating FGF2 were suggested to have prognostic value in hematological malignancies, lung cancer, head and neck cancer and melanoma." (PMID 25609197, 2015). "FGF-2 was already known as a cytokine actively produced by melanoma cells." (PMID 25560632, 2015). "Thus, FGF2 is commonly considered one of the potential targets for treating melanoma, and may be used with other targets to synergistically enhance therapeutic efficacy." (PMID 31035725, 2019). "It was suggested that the higher level of FGF2 in the microenvironment of dermal nevus-derived melanocytes allowed melanocytes to adapt to grow in the dermis, which might be important for the development of melanoma." (PMID 31167513, 2019). "In addition, the aggressiveness of melanoma is due to Fgf2 induced α5 integrin expression." (PMID 28107390, 2017). "Fibroblast growth factor-2 (FGF-2) is overexpressed in human melanoma and may be induced by an increased release by tumor cells of matrix metalloproteinases (MMPs) which, in turn, degrade extracellular matrix inducing the release of FGF-2 stored there as an inactive form." (PMID 20631829, 2010). "First, CAFs secrete cytokines that favor melanoma invasion, including IL-6, IL-8, transforming TGF-β, β-catenin, fibroblast growth factor-2 (FGF-2), and VEGF." (PMID 40936894, 2025). "Abnormal expression of FGF-2 (along with FGF-18) and elevated FGFR1 and FGFR3 characterize primary melanoma vs. healthy skin." (PMID 39866233, 2025). "Fourteen overlapping targets (GSK3B, MAPK1, HSPA8, VEGFA, FGF2, MTOR, and so on) were considered potential targets for the treatment of melanoma with salidroside." (PMID 40708947, 2025). "Pro-angiogenic factors, including VEGF, PlGF, FGF-2, IL-8, Ang, TGF-β, PDGF, integrins, MMPs, and PAF, modulate angiogenesis and contribute to melanoma metastasis." (PMID 38791873, 2024). "PAF also promotes angiogenesis in melanoma by stimulating the expression of VEGF and FGF2; furthermore, PAF enhances the activity of MMPs in melanoma cells, promoting the invasion of endothelial cells into surrounding tissues, thereby promoting angiogenesis." (PMID 38791873, 2024). "Studies have shown that it has a high-efficiency FGF2/FGFR inhibitory effect in lung cancer, melanoma, and multiple myeloma." (PMID 36845134, 2023). "In vivo, melanoma cells secrete a plethora of pro-angiogenic factors, including VEGF, basic fibroblast growth factor (bFGF or FGF-2), interleukin-8 (IL-8), placental growth factor (PlGF), and platelet-derived growth factor (PDGF)." (PMID 37345186, 2023). "Evidence showed that melanoma cells (A375) released fibroblast growth factor (FGF)-1 and FGF-2 and this process required copper ions by activation of phosphati-dylinositol 3-kinase (PI3K)/Akt pathway." (PMID 37004045, 2023). "CAFs are also stimulated by melanoma cells to increase the expression and secretion of large amounts of VEGF-A and FGF-2, whose levels in melanoma sera patients closely correlate with poor clinical outcomes." (PMID 34067929, 2021). "Other important factors involved in fibroblast activation and MAF formation are represented by TGF-β, PDGF, FGF-2 and FGF-19, which are highly expressed by melanoma cells." (PMID 34067929, 2021). "It has also been shown to have activity against both c-KIT and FGF2, and it has demonstrated promise in treating c-KIT-mutant melanoma, warranting further study." (PMID 33807778, 2021). "We confirmed the expression of FGF2 and activation of MEK-ERK in melanoma patients using in situ data from a clinical trial." (PMID 32344828, 2020). "We and others demonstrated the key role of growth factors such as FGF-2, PDGF, and TNF-α in controlling melanoma growth and melanoma aggressiveness." (PMID 33302400, 2020). "Other angiogenesis inducers, apart from VEGF, are the fibroblast growth factors basic fibroblast growth factor (b-FGF/FGF-2), making them a potential drug target for cancer, such as melanoma." (PMID 31052435, 2019).
melanoma (continued). "For example, highly-sulfated HS is shown to trigger cell proliferation through fibroblast growth factor 2 (FGF2) signaling, in melanoma cells." (PMID 31013618, 2019). "Inhibition of FGF2 and FGFR1 in melanoma cells in vivo induced apoptosis and blocked intratumoral angiogenesis and tumor growth." (PMID 31167513, 2019). "Co-expression of the pair FGF2 and FGFR1 in melanoma was extensively characterized in the 1980s and 1990s." (PMID 31167513, 2019). "For instance, FGF2 transcript levels were more than 100-fold higher in half of melanoma cell lines than in normal melanocytes, and FGF5 in 1/3 of melanoma cell lines." (PMID 31167513, 2019). "In addition, five genes (FGF10, FGF2, MITF, PDGFC, and PDGFD) were involved in “Melanoma”, which might be associated with the two-end black pigmentation observed in BMX pigs, which differs from most Chinese domestic pigs with black coats (China National Commission of Animal Genetic Resources, 2011)." (PMID 29955027, 2018). "CAFs exhibit increasing expressions and secretion of VEGFa, FGF2, and MMP9, promoting proliferation, migration, and tube formation of ECs, and melanoma angiogenesis." (PMID 30285793, 2018). "The loss of SOCS1 expression leads to the activation of the JAK2/STAT3 signaling pathway and overexpression of MMP-2, FGF2, and VEGF and enhanced invasion and angiogenesis of melanoma cells, consequently promoting brain metastasis." (PMID 30285793, 2018). "In melanoma patients, elevated serum levels of VEGF, FGF2, and other soluble proangiogenic factors have been demonstrated and are closely correlated with poor clinical outcome." (PMID 30285793, 2018). "In primary tumours of human melanoma patients, the expression of both FGF1 and FGF2 mRNA displayed a significant positive correlation with the expression of down-stream targets of the ATF6 and PERK branches of the UPR." (PMID 29235576, 2017). "Our data show that the UPR in metastatic melanoma cells contributes to increased FGF1 and FGF2 expression and enhances cell migration." (PMID 29235576, 2017). "RT-PCR documented mRNA expression in all the melanoma cell lines analyzed (WM115, WM266.4, and the positive controls M10 and M14) for VEGF, FGF2, CDH2, CDH5, MMP-2, MMP-9, and the two isoforms of MCAM/MUC18." (PMID 28107182, 2017). "Engagement of MyD88 in activated murine melanoma cells triggers an angiogenic program that rely on the secretion of trophic factors for vascular cells, including VEGF, FGF-2, and CXCL15." (PMID 28662055, 2017). "In the present study, we show that CDV inhibits the metastatic growth of virus-independent, FGF2-driven FGF2-T-MAE and melanoma B16 tumors." (PMID 25609197, 2015). "We provide evidence of FGF-2, CXCL-1, IL-8, and VEGF-A participation in the activity of melanoma cells on keratinocytes." (PMID 25560632, 2015). "Secretion of various angiogenic cytokines, i.e. VEGF-A, FGF-2, PGF-1 and -2, IL-8, and TGF-1 by melanoma cells promote the angiogenic switch and has been correlated to transition from the radial to the vertical growth phase, and to the metastatic phase." (PMID 20631829, 2010). "Numerous studies have demonstrated aberrant expression of FGF-2 and FGF18, as well as increased FGFR1 and FGFR3 levels, in primitive melanoma samples compared to normal skin tissue, and a significant relationship between high microvascular density and expression of FGFR4 has been demonstrated." (PMID 38791873, 2024). "In addition, some studies have indicated that FGF2 regulates angiogenesis through the JAK2/STAT3 signaling pathways in both lung cancer and melanoma." (PMID 39075612, 2024). "Among all cell lines tested in this study, FGFR1 was highly expressed in EGFR + NSCLC NCI-H1650, HCC827, NCI-H1975, and HER2 + BC HCC1569 cells and BRAF+melanoma RPMI-7951, IGR-39, and SK-MEL-3 cells, and FGF2 was highly expressed in NCI-H1650, HCC827, HCC1569, RPMI-7951, and IGR-39 cells." (PMID 37880373, 2023).
melanoma (continued). "In addition, exosomal miR-155 derived from melanoma cells upregulated the expression of proangiogenic factors, such as VEGF, FGF2, MMP9, in CAFs by targeting SOCS1/JAK2/STAT3 signaling pathway, which resulted in the increase of melanoma angiogenesis." (PMID 32489584, 2020). "Using three melanoma cell lines which are dependent on oncogenic KIT, we showed that FGF2 drastically reduced the effect of the different KIT inhibitors pointing to an important role of the FGF2/FGFR axis in the resistance to KIT inhibitors." (PMID 32344828, 2020). "Early studies indicated that FGF2/FGFR1 might be of importance for autocrine growth control and melanoma progression." (PMID 31167513, 2019). "PSS inhibited FGF2-mediated angiogenesis in a rat aortic ring model and suppressed FGF2-mediated invasion, but not the migration of murine melanoma B16-F10 cells." (PMID 31035725, 2019). "In a mouse model, when FGF2 was injected at the melanoma inoculation site during the initial phase of tumor growth, both, VEGF-A-dependent neovascularization of the host stroma and melanoma metastasis were enhanced." (PMID 31167513, 2019). "Microarray and GSEA data were validated by examining FGF1 and FGF2 expression in non-metastatic and metastatic melanoma cells after 4-PBA treatment." (PMID 29235576, 2017). "FGF2 is a growth factor produced by melanoma cells but not by normal melanocytes, that activates the FGFR1 receptor." (PMID 25763355, 2015). "Human melanoma commonly expresses high levels of FGFR1 and FGF2." (PMID 26056081, 2015). "Similarly, disintegrins molecules containing the RGD motif are known to block FGF-2-induced angiogenesis and B16F10 melanoma lung metastasis development in mice." (PMID 21984914, 2011). "RGDS-treatment (48 h, 500 μg/ml) increased the percentage of cells in sub-G1-phase from 3% (with FGF-2 alone) to 13.2% (with FGF-2 and RGDS), indicating that RGDS may induce apoptosis in melanoma cells, in the presence of FGF-2." (PMID 20412563, 2010). "The IRES from FGF-2 did however induce the expression of exogenous cDNA in human melanoma cells without any positive or negative regulation from the other IRESs present within the vectors." (PMID 15279677, 2004). "However, high or low expression of ANGPT1, PDGFA, and FGF2 has no impact on the survival probability of patients with primary melanoma." (PMID 34102002, 2021). "Melanoma-like lesions appeared when FGF2 overexpression was combined with UVB but not UVA." (PMID 31167513, 2019). "Patient-derived BRAFV600E melanoma cells could grow without serum and exogenous growth factors, FGF2, EGF (epidermal growth factor), and HGF (hepatocyte growth factor), for at least 4 months without substantial changes in viability and cell phenotype." (PMID 31167513, 2019). "However, no studies have investigated the effects of PSS on FGF2-mediated functional regulation on a highly metastatic B16-F10 melanoma model and the related tumor microenvironment." (PMID 31035725, 2019). "Together, these data support a FGF-2-induced conversion of B cells into a tumor-supportive phenotype which, with IGF-1 as critical key growth factor, reciprocally provides sustained pro-inflammatory and pro-tumorigenic signals to melanoma cells leading to activation of FGFR-3." (PMID 28928360, 2017). "Induction of FGF-2 and FGFR-3 expressions in melanoma cells could be detected from 48 h on." (PMID 28928360, 2017). "To investigate whether FGF2 produced by fibroblasts upon A2BR stimulation could influence tumor cell proliferation, we performed MTT assays in B16.F10 melanoma cells co-cultured with tumor-isolated fibroblasts stimulated with 10 nM Bay60-6583 or vehicle (Ctr) for 24 hours or 48 hours." (PMID 27590504, 2016). "Indeed, catecholamine stimulation could enhance melanoma cells release of cytokines, such as IL-6, IL-8, VEGF-A and FGF-2, that sustain inflammatory, angiogenic and motility tasks." (PMID 25474135, 2015).
melanoma (continued). "Although we did not directly show that blocking the FGF2/FGFR axis had an effect on tumor growth, it was recently shown that ponatinib, a dual KIT and FGFR inhibitor, caused much stronger inhibition of KIT-mutation-bearing melanoma in vivo than imatinib agreeing with our results." (PMID 32344828, 2020). "TESSs have been used to show that melanoma cells expressing the fibroblast growth factor-2 (FGF-2) proliferate at a higher rate and are more invasive than those not expressing FGF-2." (PMID 38589876, 2024). "Pretreatment with BRAFi did not change the ability of 2 of 3 tested melanoma cell lines to induce IGF-1 expression in NB cells; one cell line lost this ability presumably due to modulation of FGF-2 activity." (PMID 28928360, 2017). "Neither the cell cycle nor the activity of pathways important for melanoma maintenance, such as MAPK-ERK, WNT (wingless/integrated)/β-catenin, and NF-κB (nuclear factor kappa B), were affected by the absence or presence of FGF2, HGF, and EGF used alone or in combination." (PMID 31167513, 2019). "Genes coding proteins such as FGF-2, VEGF-A, IL-8, and CXCL-1 have been found upregulated not only in tested BLM and NCSC but also in other melanoma cell lines (with the only exception of VEGF-A in primary culture of ascitic melanoma cells)." (PMID 25560632, 2015). "The present data resulted in the conclusion that the tumor-conditioned medium obtained from breast ductal adenocarcinoma and melanoma cells did not act on myoepithelial cell differentiation and function, which was revealed by the lack of increase in α-SMA and FGF-2 expression, respectively." (PMID 25435982, 2015). "The tumor-conditioned medium harvested from breast ductal adenocarcinoma and melanoma did not affect myoepithelial cell differentiation and function, which was reflected by the fact that there was no observed increase in α-SMA and FGF-2 expression, respectively." (PMID 25435982, 2015).